RNU6-1277P (RNA, U6 small nuclear 1277, pseudogene)
Gene: Small nuclear RNA gene on chromosome 14 (37,827,798 to 37,827,904, reverse strand). Ensembl gene ENSG00000201431.
Homologues: Orthologues: chimpanzee U6 (95% identical), macaque U6 (92% identical), guinea pig U6 (78% identical), dog U6 (76% identical). Paralogues in human: RNU6-166P (87% identical), RNU6-439P (86% identical), RNU6-26P (85% identical), RNU6-41P (85% identical), RNU6-1013P (84% identical), RNU6-15P (84% identical), RNU6-574P (84% identical), RNU6-637P (84% identical), RNU6-854P (84% identical), RNU6-946P (84% identical), RNU6-1011P (83% identical), RNU6-12P (83% identical), and 1289 more.